ENSG00000259529 (novel transcript)
Gene: Protein-coding gene on chromosome 14 (24,147,548 to 24,166,452, forward strand). Ensembl gene ENSG00000259529.
Genetic constraint (gnomAD): Missense variants: 1,118 observed, 1,432.9 expected, observed/expected ratio (o/e) 0.78, 90% interval 0.74 to 0.82. Synonymous variants: 582 observed, 566.98 expected, observed/expected ratio (o/e) 1.03, 90% interval 0.96 to 1.1.